IL7 (interleukin 7)
Diseases named in the same sentence as IL7 in open-access papers (continued):
Sharing a sentence is not in itself a finding about the gene and the disease.
tuberculosis (14 papers, 2012 to 2024). A chronic, recurrent infection caused by the bacterium Mycobacterium tuberculosis. "When IL-7 was added to the traditional tuberculosis vaccine, treatment with the recombinant adeno-associated virus (rAAV)-IL-7 mixed subunit vaccine resulted in significantly increased Bach2 expression at the beginning of CD8 + T-cell development." (PMID 38459508, 2024). "We conclude that diminished soluble IL-7R and increased IL-7 plasma concentrations, as well as decreased membrane-associated IL-7R expression in T cells, reflect impaired T-cell sensitivity to IL-7 in tuberculosis patients." (PMID 28582466, 2017). "We concluded that expression of T-cell exhaustion marker SOCS3 was increased in tuberculosis patients during therapy but was only moderately associated with aberrant IL-7 plasma concentrations." (PMID 28582466, 2017). "Hence there was no indication for an association between IL-6 plasma concentrations and impaired IL-7 T-cell response of tuberculosis patients." (PMID 28582466, 2017). "Finally, mRNA expression of exhaustion markers was compared in CD4+ T cells between the cohorts to evaluate a possible causative role of T-cell exhaustion for impaired IL-7 response in tuberculosis." (PMID 28582466, 2017). "Given the described regulatory influence of IL-7/sIL-7R on mIL-7R expression, we speculate that IL-7 and sIL-7R plasma level alterations caused by tuberculosis disrupted this dependency that indicates the homeostatic balance in healthy individuals." (PMID 28582466, 2017). "In conclusion, the integration of IL-7 and IL-15 with existing tuberculosis vaccines has shown significant promise in enhancing immune responses and strengthening the defense against M. tuberculosis infections." (PMID 38793728, 2024). "The potential of rAd-IL-7-Linker-IL-15 to augment the efficacy of tuberculosis subunit vaccines relies on its ability to strengthen central memory-like T cells, thereby providing enduring protection against M. tuberculosis." (PMID 38793728, 2024). "Several studies have shown that IL7 can drive the differentiation of naive T-cells into a memory phenotype, specifically in infections such as Leishmaniasis and tuberculosis." (PMID 38554147, 2024). "Tuberculosis patients showed significantly increased IL-7 concentrations prior to therapy as compared to healthy contacts (p < 0.001)." (PMID 28582466, 2017). "In the presented study, we identified alterations in the IL-7 pathway and impaired T-cell response to IL-7 co-stimulation in tuberculosis patients." (PMID 28582466, 2017). "Despite IL-7 being available at higher plasma levels among tuberculosis patients, the T-cell response to IL-7 was impaired when compared to healthy contacts." (PMID 28582466, 2017). "We detected lower STAT5 phosphorylation and showed also impaired IL-7 promoted cytokine release in T cells from tuberculosis patients." (PMID 28582466, 2017). "Correct prediction of tuberculosis patients and healthy contacts was achieved for 73% of all donors, and IL-7 was about two times more influential on prediction than sIL-7R." (PMID 28582466, 2017). "We found a significantly stronger effect of IL-7 on cytokine release in healthy contacts as compared to tuberculosis patients (p = 0.02)." (PMID 28582466, 2017). "First, we detected higher IL-7 plasma concentrations in tuberculosis patients that decreased during therapy and recovery." (PMID 28582466, 2017). "We determined sIL-7R and IL-7 plasma concentrations and mIL-7R expression of T cells from tuberculosis patients—before, during, and after chemotherapy—and compared these to healthy contacts." (PMID 28582466, 2017). "Tuberculosis patients had lower soluble IL-7R (p < 0.001) and higher IL-7 (p < 0.001) plasma concentrations as compared to healthy contacts." (PMID 28582466, 2017). "This present study aimed to elucidate a possible role of IL-7 modulated T-cell responses in human tuberculosis." (PMID 28582466, 2017).
tuberculosis (continued). "We describe aberrant IL-7/soluble IL-7R expression and impaired IL-7-mediated T-cell functions in tuberculosis patients with similarities and differences to described IL-7 dysregulation seen in patients with AIDS." (PMID 28582466, 2017). "To evaluate the effect of IL-7 signalling, we recruited a second cohort of tuberculosis patients (n = 22) or healthy contacts (n = 24)." (PMID 28582466, 2017). "Comparison of tuberculosis patients and healthy contacts revealed moderate discrimination capacity for both sIL-7R (AUC = 0.67) and IL-7 (AUC = 0.73) using Receiver Operating Characteristic (ROC) analysis." (PMID 28582466, 2017). "Here we provide first evidence that IL-7 mediated increased sensitivity of T cells to stimulation (e.g. by decreasing the T-cell receptor activation threshold) was impaired in tuberculosis patients." (PMID 28582466, 2017). "We evaluated the utility of IL-7 and sIL-7R plasma concentrations as biomarkers for diagnosis of active tuberculosis using ROC curve and Random Forest-based statistics." (PMID 28582466, 2017). "Our investigations provide evidence for reduced mIL-7R expression and impaired IL-7 co-stimulatory effects on T cells from tuberculosis patients." (PMID 28582466, 2017). "Initial results indicating a role of IL-7 during T-cell immunity against tuberculosis were derived from animal models." (PMID 28582466, 2017). "In order to evaluate the potential impact of IL-7 on tuberculosis, we characterised various parameters involved in the IL-7-response of tuberculosis patients and healthy contacts." (PMID 28582466, 2017). "Increased IL-7 and soluble IL-7R expression in pulmonary tissue of primates with tuberculosis was found, indicating a possible role of IL-7 metabolism in tuberculosis pathogenesis." (PMID 28582466, 2017). "The heightened protection observed with this combined approach was associated with increased Mtb32-specific IFN-γ-secreting CD4+ and CD8+ T-cell responses in the lungs and spleens, indicating the potential of IL-7-nFc as a promising adjunct for tuberculosis DNA vaccines in clinical applications." (PMID 38793728, 2024). "Therefore, fusion cytokine IL-7-Linker-IL-15 developed as an adjuvant need to be explored for triggering a stronger long-term cellular immune response against tuberculosis." (PMID 33271822, 2020). "Consequently we next determined IL-7 plasma concentrations in tuberculosis patients and healthy contacts." (PMID 28582466, 2017). "Here we investigated the role of IL-7/IL-7R on T-cell immunity in human tuberculosis." (PMID 28582466, 2017). "Hence we set an arbitrary threshold (15 pg/ml) and compared IL-6high and IL-6low tuberculosis patients for IL-7-promoted T-cell responses." (PMID 28582466, 2017). "Since normalization of low sIL-7R and high IL-7 plasma concentrations during recovery from tuberculosis was found, these parameters may qualify as biomarker candidates for successful tuberculosis chemotherapy." (PMID 28582466, 2017). "This indicated different mechanisms involved in IL-7 and sIL-7R regulation during tuberculosis." (PMID 28582466, 2017). "Our study contributed to the characterisation of impaired IL-7 T-cell response that may indeed counteract IL-7 treatment in tuberculosis." (PMID 28582466, 2017). "Overall, our study suggests that IL-7 and transcriptional factors Id3 and Bcl6 help the TB subunit vaccine to induce long-term immune memory, which contributes to providing immune protection against M. tuberculosis infection." (PMID 33562631, 2021). "For the first time, our study demonstrates that supplementation of TB protein-subunit vaccine with rAd- IL-7-Linker-IL-15 would induce more TCM like cells and improve its protective efficacy against M. tuberculosis." (PMID 33271822, 2020). "Therefore impaired mIL-7R signaling may contribute to tuberculin skin test anergy described for tuberculosis patients but additional studies are needed to further clarify the exact role of IL-7." (PMID 28582466, 2017).
tuberculosis (continued). "Functional in vitro tests indicated diminished IL-7-induced STAT5 phosphorylation and impaired IL-7-promoted cytokine release of Mycobacterium tuberculosis-specific CD4+ T cells from tuberculosis patients." (PMID 28582466, 2017). "Next, we measured IL-7-induced STAT5 phosphorylation and detected decreased phosphorylated STAT5 in CD4+ T cells from tuberculosis patients as compared to healthy contacts (p = 0.04)." (PMID 28582466, 2017). "Previously, we identified SOCS3 as a marker of CD4+ T cells in tuberculosis, and others described SOCS3 as a central regulator of T-cell exhaustion and target of IL-7 in chronic viral infections." (PMID 28582466, 2017). "However, we would speculate that impaired T-cell responses to IL-7 contributed to the phenomenon of diminished tuberculin reactivity in tuberculosis patients as this in vivo test would be better reflected by IL-7-supplemented PPD stimulation in our in vitro assay." (PMID 28582466, 2017). "Previously published data reports that IL-7 is elevated in patients with tuberculosis compared to latent TB or healthy controls, but in contrast other studies report that IL-7 response to stimulation with TB antigen displayed diminished cytokine levels compared to healthy controls." (PMID 28448542, 2017). "Therefore, IL-7 and transcription factors Id3 and Bcl6 could help the TB subunit vaccine to induce long-term immune memory, which would provide long-term immune protection against M. tuberculosis infection." (PMID 33562631, 2021). "In the present study, we did not detect a correlation between IL-7 and sIL-7R plasma levels in tuberculosis patients or healthy contacts, although both factors were affected during tuberculosis pathogenesis." (PMID 28582466, 2017). "Our findings demonstrate that availability of IL-7 alone is not sufficient to promote protective T-cell immunity against tuberculosis." (PMID 28582466, 2017). "In accordance, no dependency was detected between IL-7 and sIL-7R plasma concentrations for tuberculosis patients or healthy contacts." (PMID 28582466, 2017). "We provide initial evidence that IL-7-availability is not critical during tuberculosis." (PMID 28582466, 2017). "However, a comprehensive understanding of the possible role of IL-7 or IL-7R functions in human tuberculosis has not yet been developed." (PMID 28582466, 2017). "However, co-stimulation with IL-7 induced increased proportions IFNγ-producing T cells solely in the study group of healthy contacts (p = 0.003), but not in tuberculosis patients (p = 0.94)." (PMID 28582466, 2017). "However, we did not detect IL-7 response differences between IL-6high and IL-6low subgroups among tuberculosis patients." (PMID 28582466, 2017).
severe combined immunodeficiency (13 papers, 2011 to 2024). Severe combined immunodeficiency (SCID) comprises a group of rare monogenic primary immunodeficiency disorders characterized by a lack of functional peripheral T lymphocytes resulting in early-onset severe respiratory infections and failure to thrive. "We report 6 adults (aged 22 to 59 years) from 4 kindreds and 3 ancestries (Colombian, Israeli Arab, Japanese) carrying homozygous IL7 loss-of-function variants resulting in combined immunodeficiency (CID)." (PMID 39352394, 2024). "The loss of IL-7 signaling causes severe combined immunodeficiency, whereas gain-of-function alterations in the pathway contribute to malignant transformation of lymphocytes." (PMID 34066732, 2021). "Despite the function of Il7 in human B-cell development being somewhat disputed, inactivating mutations in the common gamma chain results in severe combined immunodeficiency in humans and activating mutations in the IL7 signaling pathway are commonly detected in human malignancies." (PMID 29966360, 2018). "JAK3 knock-out mice are found to develop severe combined immunodeficiency (SCID) due to impairment in B cell development associated with IL-2, IL-4, IL-7, IL-9, and IL-15 receptor signaling." (PMID 38380328, 2024). "All these components involved in IL-7 signaling have been implicated in several diseases, such as severe combined immunodeficiency (SCID), autoimmune diseases, and cancers." (PMID 28127156, 2017). "Disrupting IL-7 signalling can result in profoundly impaired immunity as seen in patients with T-B+NK+ Severe Combined Immunodeficiency (SCID), a genetic defect that results in inactivation of the IL-7Rα signalling pathway." (PMID 21920046, 2011). "Inactivation of IL-7 or IL-7R results in severe combined immunodeficiency (SCID)." (PMID 35581375, 2022). "Interestingly, dysregulation of IL-7 signaling through retrovirally encoded γc has been considered a possible mechanism of leukaemogenesis after γc-gene therapy, because IL-7 levels are elevated in patients with severe combined immunodeficiency (SCID)." (PMID 30373315, 2018). "The critical role of IL-7 in T cell development is evidenced by the finding that IL-7 receptor mutations lead to an absence of T cells and the development of severe combined immunodeficiency (SCID)." (PMID 24213115, 2011). "Interleukin 7 (IL‐7) expression was high in the presence of TSC, and it is known that IL‐7 is necessary for thymocyte survival and has an important role in the differentiation of T cells; indeed, mutations in IL‐7 gene and its receptor have been implicated in severe combined immunodeficiency." (PMID 36925684, 2023). "IL-7 is essential for T cell generation as IL-7- or IL-7R-deficient mice as well as IL-7Rα mutant patients with severe combined immunodeficiency (SCID) do not generate mature T lymphocytes." (PMID 30922400, 2019). "In this study, we report a 4-month-old boy with T−B+NK− severe combined immunodeficiency (SCID) due to a novel mutation in exon 2 of IL2RG, the gene encoding the interleukin (IL) common gamma chain (γc) of the cytokine receptors for IL-2, IL-4, IL-7, IL-9, IL-15, and IL-21." (PMID 35498802, 2022). "The absence of IL7 or any of its proximal signaling components leads to a severe combined immunodeficiency (SCID)." (PMID 25184791, 2014).
inflammatory bowel disease (12 papers, 2012 to 2025). A spectrum of small and large bowel inflammatory diseases of unknown etiology. "Individuals with inflammatory bowel disease have high levels of IL-7 and IL-7R and high activity of the colon-specific mucosal IL-7R signaling pathway." (PMID 40240976, 2025). "IL-7 signaling pathway influence anti-TNF responsiveness and T cell gut homing in inflammatory bowel disease." (PMID 35850640, 2022).
non-small cell lung carcinoma (12 papers, 2006 to 2024). A group of at least three distinct histological types of lung cancer, including non-small cell squamous cell carcinoma, adenocarcinoma, and large cell carcinoma. "Aside from strong evidence that IL-7 has anti-tumor effects, some studies indicate that IL-7 might enhance tumor-progression, for instance as suggested in studies focusing on non-small cell lung cancer cells." (PMID 32849527, 2020). "Whether IL-7 induce or inhibit autophagy in non-small cell lung cancer (NSCLC) are unknown." (PMID 35778432, 2022). "In addition to the anti-apoptotic effect of IL-7, IL-7 may also promote c-Fos and c-Jun activity in cancers such as non-small cell lung cancer." (PMID 34445415, 2021). "In contrast, IL7 has been reported to promote the proliferation and survival of tumor cells by activating the JAK/STAT, PI3K/AKT and RAS/ERK signaling pathways in non-small cell lung cancer, bladder cancer and T-cell acute lymphoblastic leukemia." (PMID 37958451, 2023). "The high expression of IL-7 and IL-7R is highly positie correlated with clinic stage, lymph node metastasis, VEGF-D, LVD and poor prognosis in Non-small cell lung cancer." (PMID 21159243, 2010). "Moreover, IL-7/IL-7R-induced VEGF-D upregulation positively correlates with lymph node metastasis, clinical stages, and survival in human non-small cell lung cancer patients." (PMID 34575268, 2021).
Allergy (10 papers, 2009 to 2025). An allergy is an immune response or reaction to substances that are usually not harmful. "Thymic stromal lymphopoietin (TSLP), an interleukin 7 (IL-7)-like cytokine associated with several allergic diseases including asthma, has been suggested to be a liaison between RTIs and asthma development." (PMID 29343779, 2018). "IL-7 is a critical cytokine for the development of the group 2 innate lymphoid cells (ILC2s), which are involved in allergic diseases including AD57." (PMID 34997172, 2022). "In summary, our research characterized the memory Th2 cells in allergic diseases and suggested the presence of lung-resident memory Th2 cells that depend on IL-7 signalings." (PMID 28894184, 2017). "In fact, a daily low intake in healthy volunteers of 60 ml AndoSanTM for 12 days gave a significant 50% reduction in levels of the allergy-promoting cytokine IL-4 in blood and left the other allergy-related cytokines IL-5, IL-7 and IL-13 at negligible levels." (PMID 19416507, 2009). "Pathway analysis of the putative PDGF-BB-regulated genes showed that these had highly pleiotropic effects of potential relevance for allergies: B cell signaling, cell migration and proliferation, immune response, and cytokine-related pathways, for example, via IL-6, IL-7, IL-8, and IL-15 signaling." (PMID 35513850, 2022). "This hyporesponsiveness of ILC2s did not occur when the basal ILC2 activity was maintained by IL-2 and IL-7 without IL-33, which is a strong inducer of allergy." (PMID 30683858, 2019). "In addition, certain cytokines which induce the pathological immune stimulation status such as allergy and autoimmune disorders such as IL-2, -4, -5, and IL-7 were not changed." (PMID 26173062, 2015).